SDC1 (syndecan 1)
Diseases named in the same sentence as SDC1 in open-access papers (continued):
Sharing a sentence is not in itself a finding about the gene and the disease.
prostate carcinoma (54 papers, 2008 to 2025). A carcinoma that arises from epithelial cells of the prostate gland. "Sortilin and syndecan-1 have pivotal roles in prostate cancer development and are specifically linked to different stages of cancer progression." (PMID 41303628, 2025). "The Appl-1, Sortilin, and Syndecan-1 biomarker panel addresses critical diagnostic challenges in prostate cancer pathology by enhancing the accuracy of detection and reproducibility of Gleason grading and ISUP group assignment." (PMID 41465218, 2025). "It has been further shown that the shed of SDC1 is associated with chemotherapy resistance in castration-resistance prostate cancer." (PMID 36353562, 2022). "Nine novel candidate drivers were identified in prostate cancer of Sardinia, including mutations in the SDC1 protein (R277S) and the ATAT1 protein (D19V) observed in two of the samples for each protein." (PMID 33391440, 2021). "SDC1 overexpression in human prostate cancer was also predictive of early recurrence and was associated with tumor-specific survival, high Gleason grade, the Ki-67 mitosis marker, and Bcl-2 overexpression." (PMID 26293675, 2015). "Syndecan-1 modulates interactions with the extracellular matrix, growth factor signaling, and cellular adhesion, and its expression is associated with more aggressive disease phenotypes and poorer prognosis in prostate cancer." (PMID 41303628, 2025). "Conversely, SDC1 has been implicated in mediating EMT in prostate cancer." (PMID 38683136, 2024). "While our study provides valuable insights into the role of sortilin, syndecan-1, and associated proteins in prostate cancer cell metabolism, several limitations need to be addressed by further research, including the use of diverse cell lines, in vivo studies, and clinical validation." (PMID 37596305, 2023). "Similarly, we demonstrated high circulating pre-treatment SDC1 levels to be independently associated with poor response to docetaxel chemotherapy in patients with castration-resistant prostate cancer." (PMID 33114033, 2020). "In addition, SDC1 expression is associated with a weaker response to chemotherapy for numerous solid tumors, including breast, colorectal, and prostate cancers." (PMID 26293675, 2015). "From the one side, syndecan-1 overexpression in prostate tumours was significantly associated with early recurrence, tumour specific survival and high Gleason grade, with established features of biologically aggressive prostate cancer and poor survival." (PMID 23691363, 2013). "In addition, long-chain, polyunsaturated fatty acid-mediated cell death requires Sdc-1 and the Sdc-1 ectodomain can cause apoptosis of prostate cancer cells." (PMID 22912899, 2012). "Appl1, Sortilin and Syndecan-1 are biomarkers within the endosome-lysosome system, and immunohistochemistry (IHC) labelling of these proteins may enable improved visualisation of the complex pathologies underlying prostate cancer." (PMID 37370825, 2023). "Indeed, poor prognosis in prostate cancer has been linked to elevated biglycan and syndecan-1." (PMID 32354091, 2020). "In this study, two ADCs equipped with cytotoxic MMAE were successfully prepared to provide a proof-of-principle ADC based on sortilin and syndecan-1 for prostate cancer treatment." (PMID 41303628, 2025). "As trans-membrane proteins that recycle from endocytic compartments to the cell surface, sortilin and syndecan-1 are attractive targets for therapeutic intervention that address the two major forms of prostate cancer." (PMID 41303628, 2025). "The biomarkers Appl-1, Sortilin, and Syndecan-1 represent a transformative advancement in prostate cancer pathology assessment and are now being integrated into clinical practice in the USA." (PMID 41465218, 2025). "Here, sortilin and syndecan-1 were selected as therapeutic targets for prostate cancer due to their capacity to recognize different morphologies in cancer tissue, as well as their specific regulatory/functional roles in cell metabolism." (PMID 41303628, 2025).
prostate carcinoma (continued). "SDC1 is overexpressed in several cancer types, such as prostate cancer, colorectal cancer, and glioblastoma." (PMID 40076757, 2025). "Recently, two cell surface integral membrane proteins, sortilin and syndecan-1, were reported to define critical aspects of prostate cancer pathogenesis in patient tissue samples." (PMID 41303628, 2025). "Sortilin and syndecan-1 expression accurately define the two different morphologies in prostate cancer tissue, are critical to the process of metabolic regulation, and exhibit mechanistic/functional interactions during prostate cancer progression." (PMID 41303628, 2025). "In prostate cancer, the transcription factor Zeb1 binds to the E-box in the SDC1 promoter, suppressing its expression." (PMID 39728992, 2024). "Tissue samples from 86 patients with prostate cancer were assessed by routine haematoxylin and eosin staining and immunohistochemistry (IHC) with a biomarker panel (Appl1/Sortilin/Syndecan-1) and a PIN4 cocktail (34βE12+P63/P504S)." (PMID 37704825, 2024). "A biomarker panel comprising Appl1, Sortilin, and Syndecan-1 has recently been used to define the complex biological changes contributing to prostate cancer pathogenesis and IDCP." (PMID 37704825, 2024). "Syndecan-1, when overexpressed in advanced prostate cancer cells, promotes an invasive lipogenic phenotype by interaction with β3 integrin, facilitated by concurrent expression of MT1-MMP." (PMID 39796673, 2024). "SDC1, one of the heparan sulfate proteoglycans, is involved in the metastasis of BC, prostate cancer, endometrial cancer, and oral squamous cell carcinoma." (PMID 38002057, 2023). "Another study found that high levels of Syndecan-1 in serum were correlated with worse prostate-cancer-specific survival; additionally, they were found to be correlation with shorter survival in CRPC patients treated with docetaxel." (PMID 37371647, 2023). "The current study demonstrated that IHC-assisted grading using Appl1, Sortilin and Syndecan-1 biomarkers improved prognostic predictions in patients with prostate cancer compared to H&E." (PMID 37370825, 2023). "This multifunctional role of SDC1 as a regulator of EMT was further investigated in prostate cancer, where the concurrent upregulation of ZEB1, a repressor of SDC1 expression, and Snail, and the downregulation of SDC1 induce a mesenchymal phenotype." (PMID 36358747, 2022). "In prostate cancer, the expression of syndecan-1 in epithelial cells decreases when cells are transformed and acquire invasive properties." (PMID 35965510, 2022). "Snail signalling contributes to prostate cancer progression and metastasis through nuclear translocation of the intracellular domain of Sdc-1 in prostate cancer cells." (PMID 33922532, 2021). "In contrast, positive correlation between Snail expression and nuclear translocation of SDC1 has been reported in prostate cancer cells." (PMID 34208075, 2021). "In contrast, SDC1 mediates EMT in prostate cancer and the expression of SDC1 (and also SDC2) is correlated with EMT markers (E-cadherin, β-catenin) in prostate cancer." (PMID 34282767, 2021). "Conversely, reduced expression of SDC1 has been found in mesothelioma, non-small-cell lung cancer, prostate cancer, and sarcoma." (PMID 32916872, 2020). "In accordance, we previously found in two independent patient cohorts of bladder and prostate cancer that high soluble serum SDC1 levels are directly associated with elevated MMP-7 serum levels, which suggests MMP-7 as a major protease for SDC1 shedding." (PMID 33114033, 2020). "VCAN has been shown to be up-regulated in prostate cancer along with the PGs syndecan-1, perlecan, decorin, biglycan, neural/glial antigen, serglycin and lumican." (PMID 32354091, 2020).
prostate carcinoma (continued). "Several proteoglycans have been found to be important in prostate cancer, including versican, decorin, biglycan, lumican, and syndecan-1, and data from a range of studies implicate proteoglycan alterations to prostate cancer cell survival and metastasis." (PMID 30893936, 2019). "Together, these findings suggest that expression of SDC1 can be used as a prognostic marker for patients with localized and advanced prostate cancer." (PMID 26293675, 2015). "The most studied proteoglycans in prostate cancer include extracellular proteoglycans versican, decorin and perlecan, and cell surface proteoglycans syndecan-1 and betaglycan." (PMID 23691363, 2013). "n-3 PUFA can induce apoptosis in human prostate cancer cells by activating the nuclear receptor PPARγ and upregulating the PPARγ target gene, syndecan-1 (SDC-1)." (PMID 23762859, 2013). "Syndecan-1 is downregulated in prostate carcinoma, and transfection expression inhibits cancer growth." (PMID 24391925, 2013). "It has been suggested that n-3 PUFA induces cell apoptosis in prostate cancer via a mechanism of LOX15-mediated SDC-1-dependent suppression of PDPK1/AKT/BAD phosphorylation." (PMID 23762859, 2013). "Immunohistochemical analysis revealed intensive syndecan-1 staining in normal prostate glands, whereas the expression was significantly decreased in prostate cancer samples." (PMID 23691363, 2013). "All the data suggested the expression of syndecan-1 as a prognostic marker for patients with clinically localised prostate cancer." (PMID 23691363, 2013). "Our own studies have shown reduced expression of SDC-1 in prostate cancer cell lines compared to normal prostate epithelial cells and lower expression in androgen-dependent LNCaP cells compared to androgen-independent PC3 and DU145 cells." (PMID 23762859, 2013). "From the other side, decreased syndecan-1 expression was shown in the prostate cancer cell lines LNCaP, PC3, and DU145 compared with the normal prostate epithelial cells." (PMID 23691363, 2013). "Two recent studies suggest that Syndecan-1 correlates with increasing metastatic potential in prostate cancer patients." (PMID 22135748, 2011). "HSPGs such as Syndecan-1 and Perlecan (Pln) are involved in the regulation of tumor growth and proliferation of prostate cancer cells." (PMID 22135748, 2011). "The reciprocal interconnected regulation of sortilin and syndecan-1 may contribute to the regulation of metabolic and morphological heterogeneity observed in prostate cancer." (PMID 41303628, 2025). "For example, the combinatorial use of sortilin and syndecan-1 may prevent prostate cancer from transitioning between different forms, limit metabolic reprogramming, and restrict the cancer refractory potential." (PMID 41303628, 2025). "Rather than relying on non-specific associations, Appl-1, Sortilin, and Syndecan-1 directly mirror the underlying biological architecture and primary pathogenesis of prostate cancer." (PMID 41465218, 2025). "Syndecan-1 upregulation in advanced prostate cancer stages may enhance disease progression and therapeutic resistance by altering the levels of αvβ3 integrin and survivin." (PMID 41303628, 2025). "Using immunofluorescent labelling, the membrane-associated proteins Syndecan-1 and Sortilin, plus the glucose transporters GLUT1 and GLUT4, were observed inside/associated with TNT/cellular bridge structures connecting prostate cancer cells (in PC-3, LNCaP, LNCaP, and 22Rv1 cells, respectively)." (PMID 39858418, 2024). "In addition, overexpression of SDC1 and SDC2 were associated with more aggressive in prostate cancer and MDK-LRP1 will induce the differentiation of immunosuppressive macrophages." (PMID 37065499, 2023).
prostate carcinoma (continued). "In addition, the high level of SDC1 was also considered to be related to more aggressive tumors and a worse prognosis of prostate cancer." (PMID 36388159, 2022). "Finally, a link between miR-126 cellular levels and Sdc-1 was already found in prostate cancer cells, where Sdc-1 silencing led to decreased expression of miR-126." (PMID 34638892, 2021). "Moreover, the core EMT-TF ZEB1 was identified as a transcriptional repressor of SDC1 in prostate cancer cells." (PMID 34208075, 2021). "Although they could not explain the reason for these increased levels, they maintain that the syndecan-1 ectodomain present in the serum could be used as a biomarker to improve the prognosis of prostate cancer." (PMID 33669066, 2021). "Interestingly, ZEB1 was recently identified as a repressor of SDC1 in prostate cancer cell lines displaying EMT characteristics." (PMID 34208075, 2021). "On this topic, ZEB1 was identified as a transcriptional repressor of SDC1 in prostate cancer cells." (PMID 34208075, 2021). "Other PGs may also play a role, particular those that are up-regulated in prostate cancer, such as syndecan-1, perlecan, decorin, biglycan, neural/glial antigen 2, serglycin and lumican." (PMID 32354091, 2020). "Our finding in this current study demonstrated that when syndecan-1 is positive, a higher expression of ANXA7 further decreases survival rate, highlighting the importance of ANXA7 as an important biomarker along with syndecan-1 for the prediction of survival rates in prostate cancer patients." (PMID 30321230, 2018). "In addition, we correlated the results with the expression of the molecular markers (apoptotic and tumor survival) Ki67, Bcl-2, CD10 and syndecan-1 (CD138) for which a prognostic significance in prostate cancer has previously been suggested." (PMID 30321230, 2018). "SDC1 expression is inversely related to aggressiveness in prostate cancer (PCa)." (PMID 30065348, 2018). "Another study showed that early intervention with a Syndecan-1 inhibitor (OGT2115) or RNAi-mediated Syndecan-1 silencing in a transgenic mouse model of prostate cancer reduced the incidence of adenocarcinoma and the number of c-kit(+)/CD44(+) cells in cancer foci." (PMID 28270211, 2017). "We have previously reported that syndecan-1 (CD138) up-regulates miR-331-3p expression by directly targeting neuropilin 2 (NRP2) and nucleus accumbens-associated protein 1 (NACC1) to mediate the EMT in prostate cancer cells." (PMID 27548144, 2016). "In prostate cancer the syndecan-1 level is correlated inversely with tumor grade." (PMID 26420915, 2015). "For instance, compared to normal epithelial cells, decreased syndecan-1 expression has been found during malignant transformation of prostate cancer, and reduced cell-membrane syndecan-1 immunoreactivity was observed in many epithelial malignancies connected to various stages of tumor progression." (PMID 26420915, 2015). "Possibly, data on simultaneous disappearance of syndecan-1 from prostate cancer epithelial cells and overall increase of syndecan-1 content in tumour stroma could contribute to the understanding of the functional role of syndecan-1 in prostate carcinogenesis." (PMID 23691363, 2013). "There is very limited information about SDC-1 expression in prostate cancer." (PMID 23762859, 2013). "Analysing the literature, one could mention that almost all data on the decreased expression of syndecan-1 were obtained from the cell culture experiments in vitro, based on the prostate cancer cell lines of epithelial origin." (PMID 23691363, 2013).
prostate carcinoma (continued). "The DHA metabolites thus slow prostate cancer cell proliferation by engaging the PPARγ/syndecan-1 pathway of apoptosis and thereby may contribute to the prostate cancer-suppressing effects of not only 15-LOX but also dietary DHA." (PMID 23029040, 2012). "Syndecan-1 may also be a target of 2OST function, thereby contributing to prostate cancer progression." (PMID 22135748, 2011). "One possible explanation for this observation is that the non-malignant prostate cell line (PNT1a) may not be an ideal control, as it exhibits high expression of sortilin and syndecan-1, together with cytogenetic and partial oncogenic alterations like those observed in prostate cancer cells." (PMID 41303628, 2025). "Anti-sortilin (clone 11H8) and anti-syndecan-1 (clone 6D11) monoclonal antibodies demonstrated high specificity for epitopes on the extracellular, N-terminal domains of these respective proteins and were effectively internalized into prostate cancer cell endocytic compartments." (PMID 41303628, 2025). "Additionally, syndecan-1 was more frequently overexpressed in prostate cancer." (PMID 30321230, 2018). "However, in prostate tumours, there was a significant decrease in syndecan-1 and glypican-1 protein expressions in prostate cancer epithelial cells with the simultaneous increase of overall content of the proteoglycans in the stromal compartment of prostate tumour tissue." (PMID 23691363, 2013). "The following terms were combined in our search: prostate cancer; biomarkers; IL-17; STAT3; NRP1; LIMK1; Cofilin-1; PSMA; AMACR; CD15; Appl1; Sortilin; Syndecan-1, and p63." (PMID 37371647, 2023). "The available cohort included 114 patients with prostate cancer, whose tissue samples were ISUP graded using an H&E slide and then independently graded using Appl1, Sortilin and Syndecan-1 IHC-labelled slides." (PMID 37370825, 2023). "It has been described that syndecan-1 expression is lower in PC3 and DU145 prostate cancer cell lines than in normal prostate epithelial cells." (PMID 35965510, 2022). "For example, these pathways are involved in SDC1 activation of FGF2-FGFR1 complex formation and downstream signaling leading to malignant transformation in lymphomas, breast, and prostate cancer." (PMID 32916872, 2020). "We have previously reported that syndecan-1 (CD138) up-regulates miR-331-3p expression by directly targeting neuropilin 2 (NRP2) and NACC1 to mediate the EMT in prostate cancer cells." (PMID 30248959, 2018). "Another study found that the expression patterns of SDC1 and SDC2 changed to a granular-cytoplasmic localization in prostate cancer samples." (PMID 26293675, 2015). "In a mouse prostate cancer model, the reduction in tumor growth as a result of dietary n-3 PUFA is accompanied by an increase in the expression of secreted SDC-1." (PMID 23762859, 2013). "The anti-sortilin 11H8-MMAE and anti-syndecan-1 6D11-MMAE conjugates had a significant effect on cell viability and morphology in metastatic prostate cancer cells, when compared to an isotype control 10A3-MMAE conjugated antibody directed against an intracellular epitope on syndecan-1." (PMID 41303628, 2025). "In addition, 15-LOX-1-mediated metabolism of DHA was required to upregulate SDC-1 and to regulate the PDK/Akt signaling pathway that elicited prostate cancer cell apoptosis." (PMID 26821053, 2016). "The identification of syndecan-1 asa target gene for PPARγ in the breast and prostate cancer cellswas a novel but not unexpected finding." (PMID 18769551, 2008). "The incubation of sortilin 11H8-MMAE and syndecan-1 6D11-MMAE conjugates with prostate cell lines for 48 h showed increased toxicity in prostate cancer compared to non-malignant cell lines (e.g., 4.4 nM for 11H8 and 9.2 nM for 6D11 in PC3 cells compared to 44.6 nM for the isotype control)." (PMID 41303628, 2025).